TNF (tumor necrosis factor)
Diseases named in the same sentence as TNF in open-access papers (continued):
Sharing a sentence is not in itself a finding about the gene and the disease.
AA amyloidosis (15 papers, 2013 to 2025). Secondary amyloidosis is a form of amyloidosis, that complicates chronic inflammatory disorders (mainly rheumatoid arthritis) and is characterized by the aggregation and deposition of amyloid fibrils composed of serum amyloid A protein, an acute phase reactant. "In recent years, TNF-blocking agents have been shown to reduce the risk of development of AA amyloidosis, as well as to improve the renal outcome of AA amyloidosis, in patients with inflammatory arthritides." (PMID 33981717, 2021). "The underlying diseases of AA amyloidosis patients who were involved in the previously reported anti-TNF series were almost always RA or AS." (PMID 28834898, 2017). "A study has shown that anti-TNF drugs are effective in treating AA amyloidosis, though they may increase the risk of infection." (PMID 41374422, 2025). "With increased availability of TNF inhibitors, the incidence of AA amyloidosis appears to be declining." (PMID 33981717, 2021). "Biologic drugs for RA have been used in patients with secondary AA amyloidosis, including tumor necrosis factor and Janus kinase inhibitors, interleukin 6 blockers, and a T cell modulator." (PMID 34397890, 2021). "Since tocilizumab, a humanized anti-interleukin (IL)-6 receptor antibody, and tumor necrosis factor (TNF) inhibitors have become available as standard treatment for RA, AA amyloidosis is now a treatable and preventable disease." (PMID 33155543, 2021). "The review of biologic therapy use for AA amyloidosis secondary to RA shows that TNF inhibitors, tocilizumab, abatacept, rituximab, and a JAK inhibitor can effectively prevent organ dysfunction and increase patient survival." (PMID 34397890, 2021). "As trials for IL-6 blocking agents like TCZ and sarilumab did not meet their primary endpoints in AS, the approach of initially adding a TNF-blocking agent in those AS patients who develop AA amyloidosis seems rational." (PMID 33981717, 2021). "To date, only in small case series preliminary clinical improvement have been shown with rituximab therapy for AA amyloidosis secondary to RA that is refractory to TNF-α inhibitors (TNF-i) therapy." (PMID 30400666, 2018). "The rationale for using anti-TNFs in AA amyloidosis depends on the fact that TNF-α is a potent inducer of SAA." (PMID 28834898, 2017). "Notably, IL-6 inhibitors have demonstrated greater efficacy than TNF inhibitors in managing AA amyloidosis, as IL-6 is directly involved in stimulating SAA production." (PMID 40700073, 2025). "Secukinumab may be a new treatment option for patients with PsA-related AA amyloidosis especially in patients who are refractory or intolerant to TNF inhibitors." (PMID 36128216, 2022). "While colchicine and IL-1 antagonists are effective in AA amyloidosis associated with HPFS6–7; TNF inhibitors, IL-6 antagonists and other b-DMARDs are used in addition to cs-DMARDs in AA amyloidosis associated with RA and other inflammatory diseases for this purpose." (PMID 36128216, 2022). "Although the exact mechanism behind rituximab’s efficacy remains unknown, it may be an effective therapeutic option for serum AA amyloidosis refractory to TNF-i therapy." (PMID 30400666, 2018). "Thirty-seven patients with AA amyloidosis were started an anti-TNF for AA amyloidosis between March 2001 and June 2008 and followed until May 2016 unless deceased." (PMID 28834898, 2017). "Notably, significantly elevated levels of IL-6 and/or TNF-α may play a role in the onset of AA amyloidosis." (PMID 41374422, 2025). "A number of recent studies have verified that therapeutic strategies involving IL-6 inhibitors and TNFα inhibitors result in a decrease of serum SAA level and consequently represent an excellent therapeutic strategy for AA amyloidosis." (PMID 33679725, 2020). "Although a number of agents like azathioprine, anti TNF-alpha agents, eprodisate, anti IL-1 antagonists have been considered, there is no established treatment of AA amyloidosis by today." (PMID 28558744, 2017).
AA amyloidosis (continued). "Indeed, proinflammatory cytokines (IL-1β, IL-6, and TNF-α) produced by antitumor lymphocytes or macrophages can induce SAA production and development of AA amyloidosis." (PMID 24558629, 2013).
alcoholic cirrhosis (15 papers, 2013 to 2025). "In the present study, high circulating levels of CRP, IL-6 and TNF-α in the cirrhotic group are consistent with a chronic inflammatory state, which is typical for end-stage alcoholic liver cirrhosis." (PMID 34884173, 2021). "Functional changes among circulating MAIT cells in patients with alcoholic cirrhosis, including increased production of IL-17A and perforin, and reduced production of TNF-α." (PMID 34321090, 2021). "The MAIT cells produced markedly lower levels of TNF-α in patients with alcoholic cirrhosis (p = 0.033)." (PMID 34321090, 2021). "The present study demonstrated that MAIT cells produce more IL-17A, and less TNF-α in patients with alcoholic cirrhosis." (PMID 34321090, 2021). "Previous studies have found that biomarkers for inflammation (Interleukin-6 and Tumor Necrosis Factor α) are elevated in alcoholic cirrhosis patients and predict increasing knee pain in patients with primary osteoarthritis." (PMID 27898694, 2016). "Single-nucleotide polymorphisms in IL-1β (−511C/T), IL-10 (−592C/A), TNF-α (−308G/A, −238G/A), TGF-β1 (−509C/T) and CTLA4 (+49A/G) were assessed in a South Indian population of 181 patients with alcoholic cirrhosis and 110 controls." (PMID 26343741, 2015). "Increased serum TNF-α and IL-6 concentrations have frequently been found in alcoholic liver cirrhosis patients." (PMID 24163503, 2013). "In addition, a reduction of circulating levels of PDGF-BB, and increased levels of inflammatory markers such as CRP, IL-6 and TNFα, were observed in patients with alcoholic cirrhosis." (PMID 34884173, 2021). "The background on which tumor has developed might also be of importance when assessing the effect of anti-TNF treatment since HCC develops mainly in the liver with a previous inflammatory environment due to pathogen (HBV/HCV) or excessive alcohol consumption (alcoholic liver cirrhosis)." (PMID 33178579, 2020). "TNF has been established as a key promoter of inflammation-driven hepatocarcinogenesis in NAFLD, alcoholic cirrhosis, and chronic viral hepatitis." (PMID 29445190, 2018).
autoimmune myocarditis (15 papers, 2004 to 2024). Autoimmune myocarditis is an autoimmune disease that affects the heart. "Left stellectomy in experimental autoimmune myocarditis rats prevented arrhythmias and reduced IL-6 and TNFα levels." (PMID 38256155, 2024). "High serum levels of IL-10 alongside TNF-α have previously been seen in patients with autoimmune myocarditis, but links between elevated TNF-α and pericarditis or pericardial effusions have not been observed." (PMID 38706610, 2024). "IL-1 and TNF secreted by inflammatory cells in heart infiltrates contributed to postinfectious autoimmune myocarditis." (PMID 38256155, 2024). "Apigenin treatment ameliorated experimental autoimmune myocarditis in BALB/c mice by modulating TH1/TH2 balance through downregulation of TH1 cytokines (TNF-α, IL-2, and interferon γ) and up-regulation of TH2 cytokines (IL-4, IL-10)." (PMID 33967832, 2021). "Pro-inflammatory cytokines e.g., interleukin (IL)-6, IL-1β and tumor necrosis factor α (TNF-α) together with enhanced reactive oxygen species (ROS) production play a crucial role in the development of autoimmune myocarditis." (PMID 34122450, 2021). "Astragalus root also has been shown to have anti-inflammatory activity by decreasing the pro-inflammatory cytokine, TNF-α, although in a rat autoimmune myocarditis model and mouse diabetic model." (PMID 33291715, 2020). "TNF-α was sufficient to induce spontaneous autoimmune myocarditis in mice constitutively overexpressing this cytokine in the heart." (PMID 19587788, 2009). "TNF-α has been instrumental in overcoming genetic resistance to CB3-mediated autoimmune myocarditis and likely acts downstream of LPS signaling." (PMID 19587788, 2009). "Likewise, miR-590-3p was found to inhibit the p50 subunit of NFκB, thusly decreasing IL-6 and TNF-α expression in a model of experimental autoimmune myocarditis (EAM) in Lewis rats." (PMID 31671621, 2019). "Catechin administration decreases tumor necrosis factor (TNF-α) and Th2 cytokines secretion in the heart tissues and mitigates cardiac fibrosis in rat autoimmune myocarditis." (PMID 29497382, 2018).
autoimmune uveitis (15 papers, 2010 to 2025). An autoimmune form of uveitis (disease). "It is worth noting that IL-2, IL-6, IL-13, IL-18, IFN-γ, and TNF-α were significantly higher in the aqueous humor of children with JIA-associated autoimmune uveitis." (PMID 36969183, 2023). "Because the inflammatory cytokines IFN-γ, IL-17, and TNF-α have been implicated in the development of autoimmune uveitis in humans and in mice, we studied the effects of these cytokines on CDCP1 expression on aRPE-19 cells in vitro." (PMID 35951427, 2022). "Moreover, autoimmune uveitis in patients may be associated with polymorphisms of TNF and IL10 genes." (PMID 39684616, 2024). "The treatment options for autoimmune uveitis include topical steroids, systemic glucocorticoids, biologics such as anti-tumor necrosis factor (TNF), and immunosuppressants like methotrexate." (PMID 40691808, 2025). "TNF-α and IL-6 are indeed recognized as important mediators of ocular inflammation in the early stages of autoimmune uveitis." (PMID 39684616, 2024). "Biologics are used as IMT agents in autoimmune uveitis, and TNF-α inhibitors, in particular, have demonstrated efficacy for ocular inflammation in clinical trials." (PMID 37493653, 2023). "The eye pathology was reminiscent of autoimmune uveitis, showing similar characteristics including upregulation of TNF-α." (PMID 36969252, 2023). "Neutralization or suppression of TNFα has shown to be effective in preventing experimental autoimmune uveitis." (PMID 35998207, 2022). "TNF-α together with IL-1β and VEGF causes breakdown of blood-retinal barrier in a murine model of experimental autoimmune uveitis." (PMID 20467456, 2010). "Bortezomib, which may suppress multiple inflammatory cytokines through inhibiting NF-κB activation, hence appears to be a better anti-inflammatory agent in treatment of autoimmune uveitis than TNF-α antagonists." (PMID 25653480, 2015). "TNF-α is a major proinflammatory cytokine and plays a central role in autoimmune uveitis." (PMID 25653480, 2015). "In addition to mitochondria-targeted antioxidant therapy, our results suggest a number of potential therapeutic options for autoimmune uveitis, including blockade of TNF-α/IL-6 and PAF signaling, inhibition of prostaglandin synthesis or DHA and ascorbic acid supplementation." (PMID 39684616, 2024). "We found that bortezomib treatment in EAU mice could suppress not only TNF-α but also many other inflammatory mediators such as IL-1α, IL-1β, IL-12, IL-17, and MCP-1 in retinas so the autoimmune uveitis could be more effectively suppressed with bortezomib than with TNF-α antagonist etanercept." (PMID 25653480, 2015). "In an autoimmune uveitis murine model, AhR was shown to regulate immune responses through STAT/NF-κB signaling and the subsequent production of pro-inflammatory cytokines, including TNF-α, IL-6, and IL-1β." (PMID 41300485, 2025). "Upon activation, γδ T cells have the capacity to secrete multiple cytokines such as interleukin IL-17, tumor necrosis factor-α (TNF-α), and interferon-γ (IFN-γ), thereby playing a crucial role in modulating the immune response and contributing significantly to the pathogenesis of autoimmune uveitis." (PMID 39144656, 2024).
cerebral palsy (15 papers, 2012 to 2025). A group of disorders affecting the development of movement and posture, often accompanied by disturbances of sensation, perception, cognition, and behavior. "We performed a meta-analysis to investigate the relationship between blood tumor necrosis factor-alpha (TNF-α) levels and the risk of cerebral palsy (CP) in children." (PMID 35769363, 2022). "Increased TNF-α and IL-1β plasma and CSF levels in term infants with asphyxia have been associated with neuroradiological alterations, poor neurological status at 12 months of age, and cerebral palsy." (PMID 29233180, 2017). "Activated microglia can induce blood-brain barrier dysfunction by releasing TNF-α, which participates in the development of cerebral oedema." (PMID 35769363, 2022). "High concentration of Interleukin (IL)-1, 8, 9 and tumor necrosis factor (TNF)-α were demonstrated in neonatal blood from children with Cerebral Palsy in comparison with control children." (PMID 34434904, 2021). "In preterm neonates, elevated cord blood levels of TNF are strongly associated with moderate transient suppression of EEG power and poor neurodevelopmental outcomes, such as cerebral palsy." (PMID 32293473, 2020). "Children who develop cerebral palsy show increased blood levels of TNF-α, and TNF receptor 1 is critical for LPS-mediated sensitization to oxygen glucose deprivation in vitro." (PMID 22363841, 2012). "Previous studies have demonstrated an association between neonatal serum cytokine levels of IL-8, Il-12, TNFα and TNF-β in extremely low birth weight infants and Cerebral Palsy." (PMID 32228505, 2020).
Chlamydia infection (15 papers, 2012 to 2023). "Chlamydia infection is known to interfere with apoptosis signaling induced by various stimuli like staurosporine, etoposide, TNF-α, FAS antibody and granzyme B/perforin." (PMID 25906164, 2015). "Like other infectious organisms, Chlamydia infection of epithelial cells mucosal surface evokes proinflammatory cytokines such as interleukin (IL)-6, IL-8, and tumor necrosis factor (TNF)." (PMID 22529524, 2012). "Elevated TNF-α levels have certain effects on Chlamydia infection." (PMID 34093528, 2021). "Interestingly, tumor necrosis factor (TNF)-α, which induces apoptosis of infiltrating inflammatory cells during genital Chlamydia infection was highly expressed in ENO1 knockdown DCs (p ≤ 0.05)." (PMID 28525970, 2017). "Consistent in part with this, at 24 h post Chlamydia infection, human iPSdMs were shown, using Luminex bead-based multiplex assays, to express high levels of the pro-inflammatory cytokines IL-6 and TNFα, as well as IL-1β, chemokine IL-8 and the anti-inflammatory cytokine IL-10." (PMID 28440293, 2017). "In vitro and in vivo studies on Chlamydia infection show that a variety of cytokines, including IL, interferon (IFN), and TNF are involved in the inflammatory response and immune regulation in Chlamydia-induced diseases." (PMID 34093528, 2021). "Like for H56, the cytokines IFN-γ, IL-6 and TNF-α were among the dominating cytokines in the CAF01, GLA-SE, and IC31® groups but only IFN-γ seemed to be selectively increased upon chlamydia infection." (PMID 26791076, 2016). "The tumor necrosis factor (TNF)-related apoptosis-inducing ligand receptor (TRAIL-R) suppresses inflammation and could therefore affect the course of Chlamydia infections and their long-term sequelae." (PMID 35876584, 2022). "Because conflicting observations have been reported on the effect of Chlamydia infection on CASP8 activation downstream of death receptor ligation, we initially considered canonical necroptosis as a possible explanation for the death observed in TNF/CHX-treated infected cells." (PMID 30375511, 2019).
cognitive disorder (15 papers, 2017 to 2026). A disease affects cognitive processes. "Noteworthy, the overexpression of IL‐1, TNF‐α, and IL‐6 mRNA has previously been reported in the hippocampal and cortical brain regions of mice experiencing cognitive diseases." (PMID 38680072, 2024).
Constipation (15 papers, 2017 to 2025). Infrequent or difficult evacuation of feces. "Specifically, clinical trials and in vivo studies have reported an increase in the production of inflammatory factors, such as TNF-α and NF-κB, in the constipation group." (PMID 38998543, 2024). "Further study showed that BZYQD intervention reduced the levels of serum inflammatory factors IL-1β and TNF-α and colonic inflammatory factors IL-1β and IL-6 in constipation rats." (PMID 32317976, 2020). "In summary, this study revealed that EXQ effectively alleviated constipation by improving fecal output, alleviating the concomitant inflammatory responses by enhancing sIgA level, and reducing the levels of IL-10, TNF-α and LPS in constipated mice induced by HHPD and HHPD + atropine." (PMID 28359333, 2017). "Patients with constipation often exhibit abnormalities in the gut-brain axis and dysbiosis of the gut microbiota, which may exacerbate hippocampal damage and memory decline through inflammatory factors such as IL-6 and Tumor Necrosis Factor-alpha (TNF-α)." (PMID 40534737, 2025). "The MODEL group exhibited significantly higher expression levels of both TNF-α and IL-1β compared to the CON group (p < 0.001), suggesting that constipation triggered an inflammatory reaction." (PMID 40806066, 2025). "The increased mRNA levels of four cytokines, including tumor necrosis factor-α (TNF-α), interleukin (IL)-6, IL-4, and IL-1β, were remarkably recovered in Lop-induced constipation rats after treatment with MPC." (PMID 39857371, 2024). "The intestinal expression of IL-6, IL-1β, TNFα, PGE2, and COX-2 were increased in the constipation-induced group, whereas in the groups treated with HLp-nF1 or Dul, they were significantly decreased." (PMID 33872333, 2021). "An important factor in the pathogenesis of constipation is the dysfunction of intestinal immunoregulation, and pro-inflammatory factors (IL-1β, IL-6, IL-8, IFN-γ, TNF-α) and anti-inflammatory factor IL-10 are key indicators of the degree of inflammation in the constipation model." (PMID 40718808, 2025).